HDAC4 (histone deacetylase 4)
Diseases named in the same sentence as HDAC4 in open-access papers (continued):
Sharing a sentence is not in itself a finding about the gene and the disease.
gastric cancer (continued). "The results we obtained established that cisplatin treatment has a significant effect on HDAC4 expression in gastric cancer cells." (PMID 31703394, 2019). "Thirdly, in gastric cancer cells treated with cisplatin at a toxic dose, HDAC4 expression drops dramatically, which is supported by clinical data of the TCGA showing that HDAC4 expression is lower in tumors that have been treated with chemotherapy." (PMID 31703394, 2019). "We then investigated the expression levels of proapoptotic genes identified as co-deregulated with HDAC4 in gastric cancer patients." (PMID 31703394, 2019). "The role of HDAC4 in the resistance of gastric cancer cells to cisplatin-based chemotherapy is suggested by several observations." (PMID 31703394, 2019). "The analysis revealed that LMK235 and cisplatin were acting in synergy to induce cytotoxicity at a lower dose of both drugs (>IC50), further supporting the pro-resistance role of HDAC4 in gastric cancer." (PMID 31703394, 2019). "The proproliferative effect of HDAC4 in gastric cancer cells is consistent with that reported previously for the class I HDACs, HDAC1, -2, and -3." (PMID 24896240, 2014). "In our study, we showed that HDAC4 expression were up-regulated in gastric cancer tissues and cell lines in vitro." (PMID 24896240, 2014). "Our results provide an experimental basis for understanding the pro-tumor mechanism of HDAC4 as treatment for gastric cancer." (PMID 24896240, 2014). "We demonstrated that HDAC4 promotes gastric cancer cell progression mediated through the repression of p21." (PMID 24896240, 2014). "Second, the effect of HDAC4 on gastric cancer cell lines was examined using overexpression and knockdown." (PMID 24896240, 2014). "In conclusion, these findings identify HDAC4 as an important regulator of proliferation of gastric cancer through repression of p21 in vitro." (PMID 24896240, 2014). "We found that HDAC4 was significantly up-regulated in gastric carcinoma tissue (**P<0.01, ***P<0.001)." (PMID 24896240, 2014). "Therefore, targeted therapy based on HDAC4 would represent a novel approach for gastric cancer management." (PMID 39497715, 2024). "HDAC4 overexpressing gastric cancers were less sensitive to cisplatin." (PMID 36982651, 2023). "HDAC4 has been recently described to contribute to cisplatin resistance in gastric cancer." (PMID 36982651, 2023). "Furthermore, the regulation between MIAT/miR-29a-3p/HDAC4 was recognized to be involved in cell biological behavior and the development of gastric cancer." (PMID 36620092, 2022). "Furthermore, miRNA-140 inhibits the invasion and migration of gastric cancer cells by downregulating HDAC4." (PMID 33628799, 2021). "HDAC4 is known to mediate tumorigenesis through chromatin structure remodeling and controlling protein access to DNA in colon cancer, glioblastoma, ovarian cancer, gastric cancer, and esophageal carcinoma." (PMID 34348664, 2021). "We examined the potential molecular mechanisms that might account for the impact of HDAC4 expression on the response of gastric cancer cells to cisplatin." (PMID 31703394, 2019). "Histone deacetylase 4 (HDAC4) promotes gastric cancer progression by downregulating p21." (PMID 31575057, 2019). "Based on this observation, we chose to investigate whether the expression of HDAC4 was also deregulated in gastric cancer cells upon cisplatin treatment, since cisplatin-based therapy is a standard for the management of this type of cancer." (PMID 31703394, 2019). "Since it appeared that cisplatin reduces HDAC4 expression, we set out to determine whether modulating HDAC4 expression prior to treatment could impact on the response of gastric cancer cells to cisplatin." (PMID 31703394, 2019).
gastric cancer (continued). "Therefore, the purpose of this study was first to evaluate the expression levels of HDAC4 in human gastric cancer tissues and cell lines." (PMID 24896240, 2014). "Therefore, our results demonstrated that HDAC4 expression were up-regulated in both gastric cancer tissues and cell lines." (PMID 24896240, 2014). "HDAC4 was up-regulated in gastric cancer tissues and several gastric cancer cell lines." (PMID 24896240, 2014). "Although the HDAC4 expression pattern showed a strong variation in healthy and tumor tissues, the HDAC4 mRNA level was significantly higher in gastric cancer biopsies (GC tumors) compared to the adjacent healthy tissues (HT)." (PMID 31703394, 2019). "Moreover, HDAC4 was found to inhibit p21 expression in gastric cancer SGC-7901 cells." (PMID 24896240, 2014). "Thus, targeting the inhibition of HDAC4 activity may be a potential therapeutic approach to treat gastric cancer." (PMID 24896240, 2014). "However, the potential relevance of HDAC4 regulation of p21 expression also needs to be viewed in the context that there are multiple key factors and pathways that potentially modulate the expression of p21 in gastric cancer." (PMID 24896240, 2014). "It has been reported that DNA methylation predominantly regulated CA9 expression in gastric cancer, while histone modifications, mediated by MORC2 and HDAC4, have been documented to control CA9 transcriptional activation through histone H3 deacetylation." (PMID 38177154, 2024). "Finally, we investigated whether HDAC4 had a relationship with p21 in gastric cancer cells." (PMID 24896240, 2014). "For instance, one of the resistance factors against cisplatin in gastric cancer could be related to HDAC enzymes, especially HDAC4." (PMID 34575561, 2021). "MiR-520b-3p could target epidermal growth factor receptor (EGFR), histone deacetylase 4 (HDAC4) and calpain small subunit 1 (CAPN4) respectively to exert tumor-suppressive effects in gastric cancer, lung cancer, prostate cancer." (PMID 32497020, 2020). "In vitro experiments using MC1568, a controversial and poorly soluble inhibitor of HDAC4, confirmed that a combinatory treatment of an HDAC4 inhibitor and cisplatin produces a synergistic response in gastric cancer cells (data not shown)." (PMID 31703394, 2019). "In gastric cancer cells, low-expression of MOF and overexpression of HDAC4 were detected." (PMID 26784169, 2016). "First, we analyzed HDAC4 expression in twenty-nine paired gastric cancer and adjacent non-tumor tissues by qRT-PCR analysis and western blot." (PMID 24896240, 2014). "We observed higher expression of HDAC4 in three gastric cancer cell lines (AGS, BGC-823 and SGC-7901), compared with a normal gastric epithelium cell line (GES) (*P<0.05, **P<0.01)." (PMID 24896240, 2014). "We were not able to confirm that HDAC4 regulates CDC2 or CYCLIN B2 in gastric cancer cells." (PMID 31703394, 2019). "Taken together, our findings have revealed an important role for HDAC4 in controlling human gastric cancer cell line SGC-7901 development via regulation of p21, suggesting that alteration of HDAC4 expression and/or activity may be an important event during gastric cancer." (PMID 24896240, 2014). "However, the exact mechanism of HDAC4 in gastric cancer has not been determined." (PMID 24896240, 2014). "However, the global H4K16ac in gastric cancer cells is increased by overexpressing MOF, but not by knocking down HDAC4, suggesting that the expression of MOF might be responsible for the global histone H4K16ac in gastric carcinoma." (PMID 26784169, 2016).
ovarian carcinoma (28 papers, 2013 to 2025). A malignant neoplasm originating from the surface ovarian epithelium. "HDAC4, a member of the histone deacetylase family, encodes a protein that reportedly mediates cisplatin sensitivity in ovarian cancer." (PMID 23484053, 2013). "In general, class I HDAC1-3 are upregulated during ovarian cancer progression and correlate with a poor patient survival; while class II HDAC4 overexpression is linked with platinum resistance as well deacetylation of STAT1 in primary ovarian cancer cells isolated from ovarian cancer patients." (PMID 31426393, 2019). "This aligns with findings in ovarian cancer, where HDAC4 silencing reduced cell migration, and in colorectal cancer, where NaB inhibited EMT via miR-200, increasing E-cadherin and reducing Snail and vimentin expressions." (PMID 40143970, 2025). "Elevated levels of HDAC4 mRNA are unfavorable prognostic markers in ovarian cancer but are considered favorable in pancreatic cancer." (PMID 38911380, 2024). "Class IIa HDAC inhibition, HDAC4 inhibition in particular, has also been proposed to sensitize certain types of cancer to cisplatin, e.g., gastric and ovarian cancer." (PMID 36982651, 2023). "An anti-metastatic role of HDAC4 was also observed in ovarian cancer and is operated by the classical partner MEF2A." (PMID 36762207, 2023). "HDAC4 can promote the proliferation and migration of epithelial ovarian cancer cells via the repression of p21 on fibrillar collagen matrices." (PMID 37894746, 2023). "For instance, it has been suggested that HDAC4 is negatively correlated with prognosis in patients with cancers, including ovarian cancer, esophageal carcinoma, and hepatocellular carcinoma." (PMID 35602496, 2022). "Specifically, in a previous report, miR-545-3p sponged by lncRNA PTPRG-AS1 to target histone deacetylase 4 suppressed cell migration and invasion in epithelial ovarian cancer." (PMID 34612783, 2021). "For example, miR-545-3p, sponged by lncRNA PTPRG-AS1, inhibits cell tumorigenicity in ovarian cancer by attacking its target gene, HDAC4." (PMID 34612783, 2021). "High HDAC-4 expression has been connected with capsular invasion in malignant thyroid lesions and advanced-stage epithelial ovarian cancer." (PMID 33799478, 2021). "Apicidin reduces HDAC3 and HDAC4 expression and activity, leading to increased histone H3 and H4 acetylation in endometrial and ovarian cancer cell lines." (PMID 32365701, 2020). "For instance, HDAC4 was shown to activate STAT1 leading to platinum resistance in ovarian cancer patients-derived cell lines and resistance to etoposide in lung cancer cells." (PMID 26206152, 2015). "Use of bio-informatics tools identified 19 mRNAs potentially targeted by hsa-miR-302b, including HDAC4 gene, which has been reported to mediate cisplatin sensitivity in ovarian cancer." (PMID 23484053, 2013). "The HDACI apicidin can significantly inhibit the expression of HDAC4 in ovarian cancer SKOV3 cells." (PMID 37894746, 2023). "Besides, HDAC4 was also found to be involved in the process of platinum resistance in ovarian cancer." (PMID 35252174, 2022). "Overexpression of HDAC4 or increased nuclear location in ovarian cancer cell line-SKOV3 could promote the mRNA expression of BCL2 and inhibited the cell apoptosis." (PMID 33845782, 2021). "In addition, HDAC4 also plays an important regulatory role in cancer, such as ovarian cancer, colon cancer, and B-cell lymphoma." (PMID 31947925, 2020). "Clinical relevance among PRL-3, SOX2, and HDAC4 is validated in ovary cancer samples." (PMID 31887658, 2020). "In a previous study, we demonstrated that miR-302b acts as chemo-sensitizer in human ovarian carcinoma cell lines by targeting HDAC4, and may represent a biomarker able to predict response to cisplatin." (PMID 26623722, 2016).
ovarian carcinoma (continued). "It has been reported that HDAC4 is upregulated in cisplatin-resistant ovarian cancer cells." (PMID 25608569, 2015). "In particular, the Class IIa HDAC4 is overexpressed in EOC and is correlated to poor overall survival and/or unfavorable progress-free survival in all ovarian cancer patients (n > 1400) examined." (PMID 34359722, 2021). "For instance, HDAC4 positively regulates STAT1 activation and mediates STAT1-dependent platinum resistance in ovarian cancer." (PMID 26654227, 2015). "HDAC4 deacetylates STAT1, thereby enhancing phosphorylation and nuclear translocation of STAT1 upon cisplatin-treatment in platinum resistant ovarian cancer cells (exposure to chemotherapy)." (PMID 26654227, 2015). "MiR-140, which targets histone deacetylase 4 (HDAC4), is also reported to be down-regulated in ovarian cancer." (PMID 24782983, 2014). "Over-expressed histone deacetylase 4 (HDAC4) interacted with STAT1, decreasing the levels of STAT1 acetylation and promoting STAT1 nuclear localization, thereby leading to cisplatin resistance in ovarian cancers." (PMID 34522170, 2021). "Moreover, we analyzed HDAC4 expression in the PRL-3-low and PRL-3-high fresh ovarian cancer groups." (PMID 31887658, 2020).
glioma (25 papers, 2014 to 2024). A benign or malignant brain and spinal cord tumor that arises from glial cells (astrocytes, oligodendrocytes, ependymal cells). "Univariate Cox regression indicated that high expression levels of HDAC1, HDAC3, HDAC7 and HDAC9 were associated with poor OS of glioma, and elevated expression levels of HDAC4, HDAC5, HDAC6 and HDAC11 were associated with a favorable prognosis of glioma." (PMID 35545840, 2022). "High HDCA1/3/7 and low HDAC4/5/11 mRNA levels were significantly associated with overall survival and disease-free survival in glioma." (PMID 35359455, 2022). "Patient age, CD4+ T cell density, and HDAC3 and HDAC4 mRNA expression were associated with high-grade glioma prognosis." (PMID 35359455, 2022). "Due to HDAC4 pathogenic function in glioma and several other cancerous disorders, this receptor serves as an ideal target for therapeutic design." (PMID 31905609, 2019). "The results showed that HDAC4 expression is downregulated in high- as compared to low-grade glioma and is associated with a favorable clinical outcome." (PMID 25557107, 2015). "We propose that HDAC4 expression is closely associated with glioma grade and prognosis, with a lower HDAC4 expression significantly associated with progressive malignancy and unfavorable disease outcome, similar to what is observed in other cancers." (PMID 25557107, 2015). "PME-1 and HDAC4 are associated with the progression of human glioma." (PMID 36555359, 2022). "Our results align with a previously demonstrated better outcome for high-expressing patients of specific class IIA HDAC members, specifically in non-small cell lung carcinomas, HDAC7 in triple-negative breast cancers, and HDAC4/5 in gliomas." (PMID 39063083, 2024). "HDAC4 has previously been shown to induce cell proliferation in glioma, osteosarcoma, gastric-, esophageal-, and colon cancer, while it had only modest effects in urothelial carcinoma cell lines and multiple myeloma." (PMID 36982651, 2023). "The results of the immune combination showed that HDAC4 is highly expressed in glioma tumor tissues." (PMID 35359455, 2022). "Some studies have shown that the molecular mechanism of glioma formation involved HDAC4-mediated SP1 and KLF5 deacetylation in selective MKK7 transcription and oncogenic JNK/c-Jun cascade activation." (PMID 35359455, 2022). "HDAC4 is often dysregulated in human malignancies, and we have demonstrated down-regulated expression in glioma tissues." (PMID 36227941, 2022). "HDAC4 is frequently dysregulated in human malignancies, and we also confirmed its downregulated expression in glioma tissues." (PMID 35545840, 2022). "As reported, HDAC4 induces EMT in glioma cells and contributes to progression of esophageal carcinoma." (PMID 34986849, 2022). "Silencing of HDAC4 reactivates p21(WAF1/Cip1) and causes cancer cell growth arrest in vitro and inhibits tumor growth in an in vivo U87-MG glioma model." (PMID 30837601, 2019). "Glioma, the most deadly brain tumor has recently been shown to overexpress histone deacetylase 4 (HDAC4)." (PMID 31905609, 2019). "HDAC class IIa enzymes (HDAC4, 5, 7, 9) are important for glioma progression, invasion, responses to TMZ and radiotherapy, and prognosis." (PMID 30837601, 2019). "This work proposes novel compounds for glioma and other disorders sensitive to HDAC4 expression and provides researchers with tools to promote maximal binding affinity to the HDAC4." (PMID 31905609, 2019). "Within this family of 18 isozymes, HDAC4 is a prime target for glioma, one of the most aggressive brain tumors reported." (PMID 31905609, 2019). "The results of this work will be an asset to paving the way for further design and optimization of novel potent HDAC4 inhibitors for gliomas." (PMID 31905609, 2019).